IFNG (interferon gamma)
Diseases named in the same sentence as IFNG in open-access papers (continued):
Sharing a sentence is not in itself a finding about the gene and the disease.
colitis (917 papers, 2007 to 2026). Inflammation of the colon. "Our results demonstrate that IL-36γ stimulation of naive CD4+ T cells significantly induced IFNγ expression in vitro and was associated with augmented intestinal inflammation in vivo using the T cell transfer model of colitis." (PMID 40642091, 2025). "The conditional knockout of IFNGR in intestinal epithelial cells was recently shown to markedly enhance spontaneous and colitis-associated tumorigenesis in mice, providing conclusive evidence for the anticancer role of IFNγ in CRC." (PMID 38962090, 2024). "We isolated lymphocytes from the livers of these mice and found increased frequencies of Foxp3+ Treg in Mdr2-deficient mice upon acute DSS colitis induction and comparable frequencies of IFNγ+ and IL-17A+ CD4+ T cells." (PMID 38510236, 2024). "IFNγ is crucial for gut homeostasis and its dysregulation is linked to diverse colon pathologies, such as colitis and colorectal cancer (CRC)." (PMID 38684864, 2024). "Streptococcus sanguinis ATCC10556 and TW289 from oral Streptococcus have been shown to aggravate colitis in mice by infecting liver cells and causing interferon gamma secretion, which leads to colitis aggravation." (PMID 39131163, 2024). "Perinatal exposure to TiO2 also exacerbated the colitis, as evidenced by a reduced colon length associated with increased colonic mRNA expression and protein levels of IL-1β, IL-4, IL-12, IL-13, IFNγ and TNF-α." (PMID 37996842, 2023). "In checkpoint blockade colitis in humans, pathogenic IFNγ-producing CD8+ T cells are expanded from tissue-resident memory pools in the presence of expanded, albeit ineffective Tregs." (PMID 37461742, 2023). "This defect can be attributed to aberrant IFNg expression in Foxo1-deficient Tregs since secondary deletion of IFNg rescues Treg-dependent colitis prevention." (PMID 33604081, 2021). "Interferon gamma–producing CD8+ TRM cells are a pathological hallmark of ICI-colitis and a novel target for therapy." (PMID 34147519, 2021). "We postulate that activated CD8+ TRM cells in ICI-colitis are responding to commensal or pathogenic microbes, and that this results in high levels of cellular activation and IFNG signaling that propagates downstream and widespread tissue activation." (PMID 34147519, 2021). "In previous work, we identified liposomes containing the synthetic TLR ligands GLA and 3M-052 as a promising adjuvant formulation to promote antigen-specific IFNγ/IL-17A-associated immunogenicity and protective efficacy in the amebic colitis mouse model." (PMID 34248966, 2021). "In contrast, Yeti mice with prolonged expression of IFNγ via modification of their 3′ untranslated region (UTR) exhibit increased susceptibility to DSS-induced colitis." (PMID 33513946, 2021). "In vivo, effector functions were compromised since adoptive transfer of NCOR1-deficient CD4+ T cells resulted in attenuated colitis due to lower frequencies of IFNγ+ and IFNγ+IL-17A+ Th cells and overall reduced CD4+ T cell numbers." (PMID 32318068, 2020). "These mice are prone to develop a severe disease in the experimental model of colitis, in which IFNγ-secreting B cells have a pathogenic role." (PMID 33584696, 2020). "Dab2 it has been identified as a IFNγ-responsive gene in macrophages and increased mucosal IFNγ is a hallmark of Crohn’s disease and experimental murine colitis." (PMID 33178208, 2020). "Functional role of IFNγ as a signature Th1 cytokine is also implicated in pro-inflammatory responses and disease conditions like colitis." (PMID 31488616, 2019). "ILC3s that produced IFNγ were associated with inflammatory responses in murine infection with bacteria or bacteria-driven murine colitis." (PMID 30984202, 2019). "In a preclinical model of colitis-associated colorectal cancer, PD-L1 emerged to be mainly expressed by tumor-infiltrating M-MDSCs (CD11b+Ly6C+ cells) in response to IFNγ via STAT1-IRF1 axis." (PMID 31130949, 2019).
colitis (continued). "IL23 expression is required on T cells to trigger colitis, which is associated with IFNγ and IL17 co-expression." (PMID 31191543, 2019). "Consistently, we found that the recipient mice transferred with Foxp1-deficient iTreg cells developed more severe colitis, indicated by the greater body weight loss and more IFNγ- or IL-17A–producing T cells in the colons." (PMID 31125332, 2019). "Collectively, we demonstrate that targeting exacerbated IL17 secretion in an IFNγ-deficient environment has disease-limiting properties in the CD4 T cell transfer mouse model of colitis." (PMID 29416538, 2018). "For this purpose, colitis was induced in Rag1−/−Ifng+/+ or Rag1−/−Ifng−/− mice by adoptive transfer of IFNγ-sufficient or -deficient CD4 CD45RBhi T cells." (PMID 29416538, 2018). "Taken together, these data suggest that the combined loss of iNKT cells and dysregulated IFNγ production can induce a decrease in protective Foxp3+CD25+CD4+ T cells during DSS-induced colitis." (PMID 30333822, 2018). "The pathogenic potential of Th1 and Th17 cells actually depends on the colitis model studied, and it has recently been shown that IFNγ production is necessary in Th17 cells to cause colitis." (PMID 30619314, 2018). "In the absence of IFNγ, intestinal inflammation in CD4 T cell recipient mice was associated with enhanced IL17 responses; consequently, targeting IL17 signaling in IFNγ-deficient mice reduced T cell-mediated colitis." (PMID 29416538, 2018). "This shows that IL-18 signaling after Nlrp1 activation increases the disease severity of DSS-colitis, associated with increased IFNγ-producing Th1 cells." (PMID 30214011, 2018). "Among effector T cells (Teffs), both T helper (Th) 1 and Th17 cells, which produce IFNγ and IL-17, respectively, have been implicated in the pathogenesis of experimental colitis, whereas regulatory T cells (Tregs) inhibit colitis development." (PMID 26230654, 2015). "Simultaneously, the authors also discovered a lowered circulating level of pro-inflammatory IL-1β, IL-6, and IL-17α, along with an increased level of anti-inflammatory IL-12, IFNγ, and IL-10 in the context of colitis-associated cancer, suggesting ameliorated systemic inflammation." (PMID 41557725, 2026). "Notably, Ccl1 has been linked to improved outcomes in DSS colitis models by inducing IFNγ expression in ILCs61." (PMID 41041542, 2025). "The colitis was exacerbated in these animals, as evidenced by a reduced colon length associated with increased colonic mRNA expression and protein levels of IL-1β, IL-4, IL-12, IL-13, IFNγ and TNF-α." (PMID 37996842, 2023). "They observed that the increased colitis was associated with increased levels of Th17 and Th1 cells, as well as interleukin 17 A (IL-17A) and interferon-gamma (IFN-γ), in the colonic mucosa of mice that have experimentally induced periodontitis when compared to control animals." (PMID 35628390, 2022). "Moreover, iNKT cells contribute to protection against IFNγ-mediated colitis by limiting an increase in pathogenic CD25+CD4+ effector T cells." (PMID 36499642, 2022). "To study immune-epithelial interactions, we stimulated EpOCs with cytokines previously associated with PSC-UC and with colitis-associated cancer, such as IFNγ and IL-22.11, 33 We confirmed that EpOCs respond to cytokine stimulation with STAT phosphorylation and gene induction." (PMID 33570127, 2021). "Our work has identified that IFNG-producing CD8+ TRM cells are a cellular hallmark of ICI-colitis." (PMID 34147519, 2021). "Furthermore, ILC3-associated IFNγ/IL-17 production in response to H. hepaticus was linked to the development of colitis highlighting a potentially deleterious role of ILC3 cytokine production." (PMID 30984202, 2019). "Importantly, while in vitro differentiated IFNγ expressing Th17 cells can induce colitis after adoptive transfer, in vitro IFNγ -deficient Th17 cells (still expressing IL17) are unable to induce disease in recipients." (PMID 29416538, 2018).
colitis (continued). "In contrast, in vivo-activated Nfat-deficient CD4 T cells were skewed toward increased IFNγ and IL-17A expression, and T cell-restricted Nfat5-deficient mice exhibited more severe pathology and enhanced IFNγ mRNA expression in lymph nodes and colon of an animal model of experimental colitis." (PMID 30538703, 2018). "We next sought to examine whether the intestinal microbiota contributes to the exacerbated colitis caused by the expanded IFNγ-producing CD4+ T-cell population in Cnb1CD4 mice." (PMID 29515579, 2018). "Moreover, an activating mutation in Nlrp1a increases IL-18 and IFNγ production, and decreases colonic butyrate to exacerbate colitis." (PMID 30214011, 2018). "Having characterized a Tpl2-dependent defect in IL-17A expression, along with the previously identified IFNγ defect, we next examined the capacity of Tpl2−/− T cells to induce disease in a T cell transfer model of colitis associated with a mixed Th1 and Th17 inflammatory response." (PMID 25781948, 2015). "Since both Th1 and Th17 cells are associated with colitis, we investigated whether Tpl2 altered the proportions of IFNγ or IL-17A positive CD4 T cells within the spleen and mesenteric lymph nodes (MLN)." (PMID 25781948, 2015). "Using a mouse model of HFD + trinitrobenzene sulfonic acid (TNBS)-induced colitis, dietary n-3 PUFAs have been shown to reduce colitis-associated disease severity and colonic mRNA expression of cytokines (IL-6, IL-17A, IL-17F, IL-21, IL-23, and IFNγ) versus corn oil in control HFD mice." (PMID 40219010, 2025). "While the transfer of Ihh HET CD4+ T cells potently induced colitis, transfer of Ihh KO CD4+ T cells showed strongly diminished colitis indicated by reduced weight loss, reduced colon thickening/shortening and reduced mucosal infiltration of T cells expressing IL-17a, IL-22 and IFNγ in the colon." (PMID 35835905, 2022). "Thus, in future studies, it will be informative to test the hypothesis that DN iNKT cells are critical for preventing IFNγ-driven colitis pathogenesis by suppressing pathogenic Foxp3−CD25+CD4+ T cell differentiation." (PMID 36499642, 2022). "This is not surprising, as one could expect that by protecting mice from developing colitis, BI119 would be acting not only against direct targets of RORγt (such as IL17A), but also on the expression of indirect targets (IFNG or S100A8) associated with the inflammatory response in colitis." (PMID 30405600, 2018). "Thus concurrent production of TNFα and IFNγ by Ndfip1-deficient Th17 cells, coupled with the observed destruction of the colon mucosa, may explain the severe weight loss seen in the colitis model." (PMID 28051111, 2017). "Likewise, DSS-induced experimental colitis has been associated with an increased percentage of Th1 and Th17 cells in the mesenteric lymph nodes, which correlates to the overexpression of pro-inflammatory cytokines such as IFNγ, IL-17A and IL-17F." (PMID 27070642, 2016). "Moreover, the increased susceptibility of IFNγ−/− mice to colitis-associated CRC could also rely on the reduced anti-tumor activity because IFN-γ activates cytotoxic NK and CD8+ T cells." (PMID 23109839, 2012). "In addition, the HF-FO diet reduced both colitis-associated disease severity and colonic mRNA expression of the Th17 cell master transcription factor (RORγτ) and critical cytokines (IL-6, IL-17A, IL-17F, IL-21, IL-23 and IFNγ) versus HF (P<0.05)." (PMID 23166761, 2012). "Dysbiosis induces an exhausted phenotype and diminished IFNγ responses in CD4+ and CD8+ T cells, promoting colitis-associated tumorigenesis." (PMID 41557725, 2026). "Further, we observed that the expansion of colonic iNKT cells persisted during DSS colitis, and that while the percentage of IFNγ producing iNKT cells was unchanged, there were significantly fewer iNKT cells expressing IL-17." (PMID 41041542, 2025). "Next, we evaluated the impact of IL-36γ-induced IFNγ secretion using the T cell-mediated colitis model." (PMID 40642091, 2025).
colitis (continued). "IFNγ is upregulated in CD and UC as well as experimental murine colitis and is thought to be a major driver of the amplified immune response seen in intestinal inflammation." (PMID 40642091, 2025). "In conclusion, our results demonstrate a potential for IL-36γ and IFNγ to be mutually targeted as therapeutics to alleviate colitis symptoms and perhaps prevent IBD, in the long run." (PMID 40642091, 2025). "This IL-36γ -induced IFNγ was responsible, at least in part, for the ability of IL-36γ to drive robust colitis induction." (PMID 40642091, 2025). "In IBD and experimental Dextran Sulfate Sodium (DSS) colitis, IFNγ contributes to vascular barrier disruption, worsening colonic inflammation and increasing intestinal blood vessel permeability which contributes to structural and functional perturbations." (PMID 40642091, 2025). "Our data corroborate these findings and demonstrate that tofacitinib inhibited intestinal IFNγ production by ILCs during C. jejuni-induced colitis." (PMID 40614970, 2025). "CPI-induced colitis is hallmarked by expansion of resident mucosal IFNγ cytotoxic CD8+ T cells, but how these arise is unclear." (PMID 38744246, 2024). "In colitis mouse models, transferring WT Treg cells was capable of suppressing colitogenic T-cell expansion and inflammatory cytokines IL-17A and IFNγ expression." (PMID 38566992, 2024). "When cotransferring naive T cells from IL-27rα−/− mice with B cells from WT mice into B6 DKO mice, there was severe colitis, and IFNγ and IL-17A expression in colonic tissue explants was increased and IL-10 expression was reduced." (PMID 38566992, 2024). "N. brasiliensis‐derived EVs were used as treatment in a mouse model of chemical‐induced colitis and demonstrated to reduce IL‐6, IL‐1β, IFNγ and IL‐17a and increase IL‐10 expression." (PMID 39113589, 2024). "A previous study in a mouse model of colitis carcinogenesis reported increased numbers of CD8+ IFNγ+ T cells during the inflammatory process, with decreased levels in the tumor and surrounding mucosa." (PMID 38999957, 2024). "Our study also showed a significant increase in colonic expression of interleukin-17A (IL-17A), as well as interferon γ (IFNγ) and tumor necrosis factor α, during colitis in mPGES-1−/− mice compared with that in WT mice." (PMID 39596393, 2024). "As an important immune stimulator and modulator, IFNγ is crucial for gut homeostasis and its dysregulation links to diverse colon pathologies, such as colitis and colorectal cancer (CRC)." (PMID 38684864, 2024). "Together, this suggests a potential regulatory role of USP28 in modulating IL22 and IFNγ expression during acute DSS-induced colitis, with implications for the involvement of the IL2 pathway in this context." (PMID 39076972, 2024). "Regulated IFNγ generation is associated with highly regulated acute GVHD based on data from GVHD disease and histopathological GVHD-associated colitis scores." (PMID 39796136, 2024). "Groundbreaking studies in mouse models of chemically-induced colitis have affirmed the importance of the vascular endothelial barrier and provided new insights into the molecular mechanisms by which IFNγ signaling can break it down." (PMID 38962090, 2024). "In LPMCs from mice with CPI colitis there was significantly increased production of IFNγ and granzyme B in comparison to control mice." (PMID 37872166, 2023). "The cytokine predicted to be most highly activated in CPI colitis was IFNγ (z Score= 6.028, FDR = 2.06 × 10−23)." (PMID 37872166, 2023). "In vivo, treatment with IFNγ potentiated the effects of IL-33, increasing colonic A-Eos frequencies to the levels observed during colitis." (PMID 36509106, 2023). "Activated T cells produce IFNγ and/or IL-17 A in the colonic LP of the T cell transfer colitis model." (PMID 38012544, 2023). "CD90-negative and CD90-low CD127+ ILC were a potential source of IL-13, IFNγ and IL-17A at steady state and upon dysbiosis- and dextran sulphate sodium-elicited colitis." (PMID 37114052, 2023).
colitis (continued). "To further analyse the phenotype of IFNγ producing lymphocytes in CPI colitis, we examined their expression of co-stimulatory molecules, co-inhibitory molecules, chemokine receptors and gut-homing integrins." (PMID 37872166, 2023). "IL23 blockade reduced the number of IFNγ producing CD4+ T cells in the colon in CPI colitis and especially IFNγ/TNFα co-producing cells." (PMID 37872166, 2023). "A reduction in colonic IL-1β, IFNγ, and mKC levels was observed in the HF-Colitis and HF-CAC groups when compared to the LF-Colitis and LF-CAC groups." (PMID 36768196, 2023). "In keeping with IFNγ playing an important role in CPI colitis, neutralisation of this cytokine significantly reduced colon mass, improved histological appearances, and reduced infiltration of Gr-1hi neutrophils." (PMID 37872166, 2023). "Previous studies about the interference of Slc11a1 polymorphism in DSS-induced colitis pointed out the role of IL6 and IFNγ in this disease." (PMID 36792680, 2023). "CPI-colitis in mice is dependent on the composition of the intestinal microbiota and by the induction of lymphocytes expressing interferon-γ (IFNγ), cytotoxicity molecules and other pro-inflammatory cytokines/chemokines." (PMID 37872166, 2023). "Mice lacking NFAT5 specifically in T cells exhibited worsened intestinal pathology in an experimental colitis model, coupled with increased interferon gamma (IFNγ) messenger RNA (mRNA) in draining lymph nodes and colon." (PMID 37287987, 2023). "In both CD4+ and CD8+ T cells, there was an increased expression of co-stimulatory molecules in IFNγ producing lymphocytes in CPI colitis." (PMID 37872166, 2023). "Interferon gamma (IFN-γ) is known to contribute to the pathogenesis of colitis through immune modulatory mechanisms, and through direct effects on endothelial and epithelial homeostasis." (PMID 36045676, 2022). "In particular, studies examining mouse and human colonic tissue have reported on IL-17A+ CD4+ T cell or IFNγ+IL-17A+ CD4+ T cell populations that has been shown to exacerbate colitis severity." (PMID 36704549, 2022). "Recent studies suggest that high levels of pro-inflammatory cytokines, including IFNγ, TNFα, IL1β, IL6, and MCP1, are implicated in DSS-induced colitis." (PMID 35888062, 2022). "Colitis was accompanied by secretion of proinflammatory cytokines (IFNγ, IL-17) and specific mRNA transcripts within the colonic mucosa." (PMID 35381031, 2022). "In the present study, we investigated the anti-inflammatory and therapeutic effects of DCL in DSS-induced colitis in mice and LPS/IFNγ-stimulated murine RAW264.7 macrophages, respectively." (PMID 35321327, 2022). "Intestinal dysfunctions, particularly those involving TLRs, IFNG, NFKB1, and TNF, have established pathogenic roles in several mouse models of colitis and in the onset of human IBD." (PMID 35732858, 2022). "In colitis mice, the mRNA levels of Il-1β (interleukin 1 beta), Ifn-γ (interferon gamma), and Tnf-α (tumor necrosis factor alpha) had increased 3–5 folds in the colon." (PMID 35889745, 2022). "Recent studies in an adoptive transfer system of Th1/Th17 colitis have shown elevated IFNγ and IL-17 in the gut when macrophages lack WASp, but the functional significance of IL-17 was not explored." (PMID 35265075, 2022). "Our study found a significant increase in colonic expression of IL-17A, as well as IFNγ and IL-2, during colitis in mPGES-1−/− mice compared with WT mice." (PMID 34983695, 2022). "In contrast, it has also been reported that IFNγ+ Treg cells induced by IL12/TGFβ effectively suppress inflammatory disease such as colitis." (PMID 36177042, 2022). "In our in vivo adoptive transfer colitis experiment we observed a decrease not only in IL-17a+ cells but also in IL-17a− IFNγ+ cells." (PMID 35835905, 2022). "DSS treatment induces Th17 cytokines (such as IL-17A) and Th1 cytokines (including IFNγ and IL-2) in the colon, and these cytokines are essential for developing colitis." (PMID 34983695, 2022).